GOLPH3 (golgi phosphoprotein 3)
Diseases named in the same sentence as GOLPH3 in open-access papers (continued):
Sharing a sentence is not in itself a finding about the gene and the disease.
tumor (continued). "Correlation analyses showed that GOLPH3 was an independent indicator for judging tumor down-staging and postoperative TRG (tumor regression grade), indicating it could predict nCRT sensitivity." (PMID 27634904, 2016). "High GOLPH3 protein expression was detected in 122 samples (68.2%) and weak or negative staining was observed in 57 tumor samples (31.8%)." (PMID 22905766, 2012). "Further studies plan on exploring the function of GOLPH3 and the mechanism for its up-regulation in ESCC tumor, and to clarify whether GOLPH3 modulates mTOR signalling and rapamycin sensitivity in ESCC." (PMID 23056210, 2012). "Additionally, SOX8 was upregulated in tumor tissues in comparison to a non-cancerous control, which again correlated with GOLPH3 levels." (PMID 38132438, 2023). "GOLPH3 expression was not correlated with gender (OR, 0.89), age (OR, 0.95), positive lymphatic metastasis (OR, 1.27), tumor size (OR, 1.12), poor differentiation of tumor (OR, 0.56) or T stage (OR, 0.70)." (PMID 34807928, 2021). "In addition, artificially forcing a negative correlation between GOLPH3 and Wls partially inhibited the tumor growth, indicating that both proteins are important for tumor development, but also that they are not the only actors involved in these phenomena." (PMID 32023813, 2020). "This evidence suggests that overexpression of GOLPH3 could result in distinct features of GOLPH3 in tumor cells compared to that of non-tumorigenic cells." (PMID 27123979, 2016). "In contrast, GOLPH3 expression did not correlate with age, gender and tumor differentiation." (PMID 22905766, 2012). "Additionally, knocking down of GOLPH3 in another tumor-related cell line, MCF7, led to similar changes in GM1 and GD1a gangliosides suggesting that GOLPH3 may have a general role in glycolipid metabolism in multiple tumor types." (PMID 36142273, 2022). "We found that the STIP1 level was increased in tumor tissue (T) compared with that in adjacent non-cancerous tissue (ANT), and correlated positively with the GOLPH3 level." (PMID 33134174, 2020). "The results also showed that the expression levels of GOLPH3 and STIP1 were higher in tumor tissues than in adjacent non-cancerous tissues." (PMID 33134174, 2020). "Using IHC and IF assays, we evaluated the expression of GOLPH3 and STIP1 in six paired tumor and adjacent non-cancerous tissue specimens from patients with PDAC." (PMID 33134174, 2020). "Real-time qPCR and Western blotting were performed to analyze the expression levels of GOLPH3 mRNA and protein in paired PDAC tumor and adjacent non-tumor tissues." (PMID 25104140, 2014). "Additionally, the negative correlation between GOLPH3 and GLI4, as well as AURKA, becomes significantly weaker in tumor samples." (PMID 40136480, 2025). "In addition, this study also found that the expression of GOLPH3 in CRC was related to clinical stage rather than gender, age, differentiation degree, lymphatic metastasis, tumor size and T stage." (PMID 34807928, 2021). "Of note, GOLM1, another protein of the Golgi apparatus that is overexpressed in some types of tumor cells, regulates EGFR recycling without affecting its glycosylation, suggesting that GOLPH3 could also directly affect EGFR recycling." (PMID 33238647, 2020).
infection (3 papers, 2015 to 2023). The state of being infected such as from the introduction of a foreign agent such as serum, vaccine, antigenic substance or organism. "The YFPc-tagged human ORFeome library was pooled together and then used to produce retroviruses to infect the GOLPH3-YFPn HTC75 expressing cell line, at a multiplicity of infection (MOI) of about 0.5." (PMID 33134174, 2020).
neurodegenerative disease (3 papers, 2015 to 2026). A disorder of the central nervous system characterized by gradual and progressive loss of neural tissue and neurologic function. "Mice with knockout of a Golgi-specific PI-4-kinase, PI4KIIα, which is closely linked with the GOLPH3 pathway, exhibit late-onset neurodegenerative disease." (PMID 34827437, 2021). "A second link to the GOLPH3 pathway arises from a substantial body of literature implicating the DNA damage response in neurodegenerative disease." (PMID 26500484, 2015). "Our discovery that the Golgi is regulated in response to DNA damage via DNA-PK activation of the GOLPH3 pathway provides a plausible link between the evidence implicating DNA damage and altered Golgi function in neurodegenerative disease." (PMID 26500484, 2015). "Moreover, knockout of a Golgi-specific PI-4-kinase, PI4KIIα, expected to interfere with GOLPH3 pathway function, leads to late onset neurodegenerative disease in mice." (PMID 26500484, 2015). "However, some of the known pathophysiology of neurodegenerative disease makes it reasonable to speculate that the GOLPH3 pathway may be involved." (PMID 26500484, 2015). "Thus, there is at least reason to speculate a role for the GOLPH3 pathway in neurodegenerative disease." (PMID 26500484, 2015). "Whether the GOLPH3 pathway plays a role in the pathophysiology of neurodegenerative disease has not been studied." (PMID 26500484, 2015).
CNS tumor (1 paper, 2020). "However, despite the growing evidence of GOLPH3 involvement in CNS tumor formation, this protein is not yet included in a standard set of their molecular biomarkers." (PMID 32023813, 2020).
gastrointestinal tumors (1 paper, 2021). "Therefore, further study of GOLPH3 as a prognostic indicator for GC and CRC is needed, and we believe that the correlation between GOLPH3 and gastrointestinal tumors will become clearer in subsequent studies." (PMID 33680216, 2021).
neurological disease (1 paper, 2021). "It has been suggested that human GOLPH3 and Golgi alterations might have a potential role in the pathophysiology of neurological disease." (PMID 34571985, 2021).
GOLPH3 also shares sentences with these, for which no sentence is quoted: liver cancer (6 papers); urothelial bladder cancer (2); adenocarcinoma (1); Alzheimer disease (1); aneurysm (1); benign cystadenomas (1); benign tumors (1); Cirrhosis (1); COVID-19 (1); dementia (1); endometrial cancer (1); Fanconi anemia (1); Globozoospermia (1); Hepatic fibrosis (1); Huntington disease (1); infertile (1); leukemia (1); malignant glioma (1); metastatic tumors (1); oral cancer (1); osteosarcoma (1); ovarian tumors (1); Parkinson disease (1); preeclampsia (1); pregnancy disorder (1); prostatic intraepithelial neoplasia (1); renal carcinoma (1); renal fibrosis (1).